RRM2 (ribonucleotide reductase regulatory subunit M2)
Diseases named in the same sentence as RRM2 in open-access papers (continued):
Sharing a sentence is not in itself a finding about the gene and the disease.
breast cancer (continued). "To further evaluate the impact of RRM2 on breast cancer patients, we evaluated the relationship between RRM2 expression levels and survival of breast cancer patients in different molecular subtypes." (PMID 35290409, 2022). "We found that the RRM2 high-expression group had poor OS in patients with the Luminal A subtype and the Normal-like subtype breast cancer patients (P<0.05)." (PMID 35290409, 2022). "We performed a KM online survival analysis and the results showed that, of all the breast cancer types, patients with high RRM2 expression and Luminal A breast cancer had the worse DMFS." (PMID 35290409, 2022). "In breast cancer, RRM2 overexpression in cancer cells promotes the formation and invasion of 3D colonies." (PMID 35898471, 2022). "We further evaluated the effects of RRM2 expression on DMFS in patients with different subtypes of breast cancer, and the results showed that in Luminal A breast cancer patients, high expression of RRM2 had worse DMFS (P < 0.05)." (PMID 35290409, 2022). "In recent years, RRM2 has gradually been discovered to be overexpressed in cancers, including breast cancer, non-small cell lung cancer, bladder cancer, and colorectal cancer." (PMID 35906548, 2022). "The Kaplan-Meier (KM) method was used to explore the relationship between high expression of RRM2 and overall survival and DMFS of breast cancer, and to study the effect of RRM2 expression on overall survival and DMFS in specific types of breast cancer." (PMID 35290409, 2022). "The expression of RRM2 was positively correlated with the grade of breast cancer grade (P = 1.57e-32)." (PMID 35290409, 2022). "In this study, we aimed to study RRM2 protein expression in different molecular subtypes of breast cancer and to correlate its expression with different prognostic parameters in breast cancer especially ER-positive subgroup." (PMID 34986845, 2022). "The qRT-PCR results showed that the relative expression of RRM2 mRNA was higher in breast cancer tissues than in adjacent normal tissues." (PMID 35290409, 2022). "In this study, we aimed to study expression of RRM2 in breast cancer and to correlate it with different clinicopathological parameters in Egyptian women." (PMID 34986845, 2022). "RRM2 plays an important role in different malignant tumors, but there are few studies in breast cancer." (PMID 35290409, 2022). "The expression of RRM2 in breast cancer can confer hormonal therapy resistance and an altered ER status." (PMID 34986845, 2022). "The high expression of RRM2 has a worse prognosis in patients with breast cancer with specific features." (PMID 35290409, 2022). "We infer that the high expression of RRM2 has an impact on the clinicopathology of breast cancer patients." (PMID 35290409, 2022). "Concordantly, previous studies showed that the expression of RRM2 (an oncogenic factor) is elevated in breast cancer tissues and cells." (PMID 34201347, 2021). "RRM2 can be used as a prognostic biomarker for a variety of cancer types, such as colon cancer and breast cancer, and overexpression of RRM2 also stimulates the migration, invasion, and proliferation of many other solid tumor cells." (PMID 33685467, 2021). "A previous study has found that RRM2 promotes breast cancer progression via activating phosphatidylinositol 3-kinase (PI3K)/AKT signaling pathway." (PMID 34895038, 2021). "Research has shown that RRM2 modulates cancer cell growth, differentiation, and metastasis, as well as drug resistance, which is overexpressed in prostate cancer, breast cancer, and cervical cancer." (PMID 34692847, 2021). "Four hub genes, namely TOP2A (p=0.036), MELK (p=0.021), PBK (p=0.043), and RRM2 (p=0.012), were upregulated during breast cancer progression from normal tissue to DCIS and downregulated during disease progression from DCIS to IDC." (PMID 34094915, 2021). "Worse overall survival was observed in breast cancer patients with increased RRM2, which had an enhancing effect on relapsing metastases." (PMID 33083904, 2021).
breast cancer (continued). "RRM2 was upregulated in DOX-resistant human breast cancer cells and peripheral blood samples of imatinib-resistant leukemia patients." (PMID 34799689, 2021). "In a study that searched the GEO database for miRNA-mRNA or lncRNA-mRNA as novel biomarkers for breast cancer, the miR-21/RRM2 axis was identified as a candidate biomarker for the diagnosis and treatment of breast cancer." (PMID 34675265, 2021). "Five hub genes, RRM2, TOP2A, PBK, MELK, and NUSAP1, which are associated with breast cancer pathogenesis, are gradually upregulated from NME to DCIS and then downregulated in IDC." (PMID 34094915, 2021). "RRM2 was found to be upregulated in various breast cancer cells, especially in triple negative breast cancer." (PMID 33083904, 2021). "Purine metabolism and related genes AMPD1 and RRM2 were enriched by combining metabolomics and transcriptomics data from the TCGA and GEO in breast cancer." (PMID 34549263, 2021). "For example, it was reported that DSCAM-AS1 promotes proliferation and decreases apoptosis of breast cancers cells by regulating miR-204-5p/RRM2 axis." (PMID 32453706, 2020). "In the Kaplan–Meier plotter bioinformatics analysis, higher expression of RAC1 and RRM2 were indicated to be an unfavorable prognostic factor for HER-2 positive breast cancer patients." (PMID 31895772, 2020). "MetOncoFit was hence able to correctly predict the upregulation of RRM2, a breast cancer biomarker that catalyzes the formation of deoxyribonucleotides." (PMID 32411371, 2020). "In this study, we identified 283 overlapping DEGs (105 up- and 178 down-regulated) and six hub genes (RRM2, CDC20, CCNB2, BUB1B, CDK1, CCNA2) associated with breast cancer tumorigenesis and progression based on multiple datasets." (PMID 33083112, 2020). "the results demonstrated RRM2 gene expression was higher in lung cancer, colorectal cancer, breast cancer, bladder cancer, sarcoma cancer, liver cancer, and others than in their matched adjacent normal tissues." (PMID 33411689, 2020). "The ribonucleotide reductase M2 subunit (RRM2) plays important role in several human cancers, including colorectal cancer, hepatocellular carcinoma, pancreatic adenocarcinoma, and breast cancer." (PMID 32180804, 2020). "Ribonucleotide reductase subunit M2 (RRM2) has been shown to be a meaningful advance factor for advanced non-small cell lung cancer and breast cancer." (PMID 31139013, 2019). "Increased level of RRM2 (red) was observed in gastrointestinal cancers, gynecological cancers, urogenital cancers, and breast cancer." (PMID 30898978, 2019). "We further investigated the prognostic value of RRM2 in breast cancer using the Kaplan–Meier Plotter, PrognoScan, and bc-GenExMiner databases." (PMID 30898978, 2019). "Further studies are needed to more precisely elucidate the value of RRM2 in evaluating breast cancer prognosis." (PMID 30898978, 2019). "The relevance between RRM2 level and clinical parameters as well as survival data in breast cancer was analyzed using the Kaplan–Meier Plotter, PrognoScan, and Breast Cancer Gene-Expression Miner (bc-GenExMiner) databases." (PMID 30898978, 2019). "While breast cancer patients with up-regulated RRM2 demonstrated worse relapse-free survival, patients with decreased RRM2 expression presented better distant metastasis-free survival." (PMID 30898978, 2019). "RR has two subunits, M1 (RRM1) and M2 (RRM2), and the latter is overexpressed in human breast carcinoma tissue (DCIS)." (PMID 31590218, 2019). "The co-expression profile of RRM2 was identified with a large cluster of 1802 genes across 61 breast carcinomas, and KIF11 is a principal correlated gene." (PMID 30898978, 2019). "Consistently, TMX decreased RRM2 abundance in several breast cancer cell lines including MDA-MB-231, MCF7 and T47D, regardless of their ERα status." (PMID 26675256, 2016). "RRM2 was negatively correlated with the survival of breast cancer patients in a dose-dependent manner." (PMID 25213022, 2014).
breast cancer (continued). "Uni- and multivariate Cox analyses of the data were used to evaluate the prognostic value of RRM2 for breast cancer patient outcome." (PMID 25213022, 2014). "Independent prognostic significance of RRM2 protein needs to be further investigated, and the prognostic performance of RRM2 (mRNA and protein) also needs to be compared with other existing breast cancer biomarkers or gene signatures." (PMID 25213022, 2014). "Here, we demonstrated that RRM2 impacted the survivability of breast cancer patients in 6 of 7 independently microarray data sets (except Chin’s set), which indicates the high reproducibility of this result." (PMID 25213022, 2014). "Our study revealed RRM2 was not only an indicator for breast cancers’ proliferation and invasiveness, but also a biomarker for undifferentiation and stem/progenitor-like phenotypes." (PMID 25213022, 2014). "In this study, we evaluated the prognostic value of RRM2 by analyzing seven independent breast cancer data sets, both individually and in a pooled manner." (PMID 25213022, 2014). "Studies have shown that a two-gene ratio (HOXB13:IL17BR) and a five-gene (BUB1B, CENPA, NEK2, RACGAP1, RRM2) molecular grade index (MGI) are predictive of clinical outcomes among early-stage breast cancer patients." (PMID 23497539, 2013). "RRM2, a ribonucleotid reductase (RR), was shown to be overexpressed in human breast carcinoma tissue (DCIS)." (PMID 21314937, 2011). "Others have suggested that RRM2 may be a potential prognostic indicator for breast cancer treatment." (PMID 38473336, 2024). "In summary, our findings strongly support the hypothesis that DDX in combination with palbociclib can potentially treat ER+ and ER− breast cancers and perhaps prevent palbociclib resistance by targeting RRM2, NF-κB, cyclin D1 and pRb." (PMID 38473336, 2024). "Previously, we found that RRM2 is upregulated in ER− and drug-resistant breast cancer cells, rationalizing our hypothesis of targeting ribonucleotide reductase for ER+ as well as ER− breast cancer treatment." (PMID 38473336, 2024). "RRM2 is also regarded as a vital component in tumor progression, a regulator of some oncogenes, and a promising tumor biomarker for many cancers, such as lung adenocarcinoma, oral squamous cell carcinoma, glioblastoma, and breast cancer." (PMID 37056349, 2023). "However, the details of the regulation between HIF-1α and RRM2 still need further study in breast cancer." (PMID 36678539, 2022). "Does the expression level of RRM2 affect the DMFS of breast cancer patients?" (PMID 35290409, 2022). "Highly expressed RRM2 is associated with poor OS and DMFS of breast cancer patients." (PMID 35290409, 2022). "In conclusion, expression RRM2 and its correlation with clinicopathological parameters could help in evaluating outcome in breast cancer especially in ER-positive subgroup and can be a potential therapeutic target in actively proliferating tumours." (PMID 34986845, 2022). "Univariate and multivariate regression analysis showed that RRM2, the number of positive lymph nodes, ER, Her-2, tumor size, and tumor stage can be used as independent prognostic factors for overall survival of patients with breast cancer." (PMID 35290409, 2022). "In breast cancer cells, RRM2 overexpression could downregulate autophagy levels, leading to the generation of cell resistance." (PMID 35204799, 2022). "RRM2 protein expression can help in evaluating outcome of breast cancer patients and could be a potential therapeutic target." (PMID 34986845, 2022). "Among all the breast cancer patients, the RRM2 high expression group had worse DMFS (P < 0.05)." (PMID 35290409, 2022). "Hence, several inhibitors of RRM2 have been developed for treatment of several cancer types including breast cancer." (PMID 34986845, 2022).
breast cancer (continued). "Owing to the complex regulatory mechanism of TTN-AS1 in breast cancer by regulating the miR-524-5p/RRM2 axis or miR-139-5p/ZEBI axis, the effect of TTN-AS1 on OSCC progression might involve other miRNAs or mRNAs, which needs to be explored further." (PMID 34606420, 2021). "In breast cancer, miR-4500 expression is down-regulated, and exerts anti-cancer effects by attenuating cancer cell migration, invasion and capillary-like tube formation of endothelial cells through regulating RRM2-dependent MAPK signaling pathway." (PMID 34229645, 2021). "Nevertheless, whether these drugs could exert therapeutic effects on breast cancer by inhibiting the over-expression of RRM2, CDK1 and CCNA2, or whether CCNB2, BUB1B and CDC20 are promising therapeutic targets still need to be supported by further research." (PMID 33083112, 2020). "Furthermore, RRM2 over-expression promoted the proliferative activity, migratory and invasive capabilities of breast cancer cells." (PMID 33411689, 2020). "Interestingly, high RRM2 gene expression is frequently detected in numerous human solid tumors, such as lung cancer, colorectal cancer, breast cancer, bladder cancer, and others." (PMID 33411689, 2020). "Therefore, in the present study, we evaluated the significance of RRM2 gene expression in breast cancer by using bioinformatics analysis of the clinical parameters and survival data in several large online databases." (PMID 30898978, 2019). "Moreover, RRM2 can be targeted and suppressed by miR‐204‐5p and RRM2 overexpression can promote the proliferation and metastasis of breast cancer cells and suppressed cell apoptosis." (PMID 31777591, 2019). "RRM2 could be used as a predictive biomarker for prognosis of breast cancer with co-expressed KIF11 gene." (PMID 30898978, 2019). "The relation between RRM2 mRNA levels and molecular subtypes of breast cancer also could be seen in the Pawitan set (p < 0.05)." (PMID 25213022, 2014). "In addition, RRM2 levels were significantly correlated with poorly differentiated breast cancers (p < 0.001)." (PMID 25213022, 2014). "Here, our pilot study indicated that inhibition of RRM2 by COH29 could significantly reduce the growth of breast cancer cells." (PMID 25213022, 2014). "Gene set enrichment analysis revealed that RRM2-high breast cancers were significantly enriched for expression of gene sets that increased in proliferation, invasiveness, undifferentiation, embryonic stem/progenitor-like phenotypes, and poor patient survival (p < 0.01)." (PMID 25213022, 2014). "According to our data, further investigating and understanding the effect of RRM2 expression on breast cancer malignancy could lead to a novel approach for treating ER-negative breast cancers." (PMID 25213022, 2014). "Moreover, the prognostic value of RRM2 was comparable to the 70-gene signature and 21-gene recurrence score for breast cancer overall, and superior to these biomarkers and pathoclinical indicators for ER-negative breast cancers." (PMID 25213022, 2014). "Only RRM2 expression, the number of positive lymph nodes, ER, Her-2, tumor size, tumor stage are significantly correlated with OS (P<0.05), and could be used as independent prognostic factors for predicting OS of breast cancer patients." (PMID 35290409, 2022). "In addition, previous studies have pointed out that high expression of RRM2 may promote chemotherapy resistance in breast cancer patients; thus, in Luminal breast cancer, high expression of RRM2 may influence the OS of patients by promoting drug resistance." (PMID 35290409, 2022). "Therefore, the high expression of RRM2 may only affect the OS of patients with specific subtypes of breast cancer." (PMID 35290409, 2022). "In addition, SNHG16/miR-30a/RRM2 axis also accelerates breast cancer cell proliferation and promote cell invasion, while miR-30a regulates liver cell proliferation and apoptosis through the suppressor of cytokine signaling 1 (SOCS-1)/JAK/STAT signaling pathway in rats with sepsis." (PMID 34895038, 2021).
breast cancer (continued). "Interestingly, AKT-induced tamoxifen resistance is reversed by RRM2 inhibition in breast cancer, suggesting that RRM2 may participate in the chemotherapy resistance of cancer cells." (PMID 31696057, 2019). "Therefore, our results suggested that lower expression of RRM2 may predict a better prognosis of breast cancer." (PMID 30898978, 2019). "In addition, it had been shown RRM2 might be a novel therapeutic target in variety of cancers, such as breast cancer, non-small cell lung cancer, and bladder cancer." (PMID 31043166, 2019). "However, the prognostic significance of RRM2 gene in breast cancer remains to be investigated." (PMID 30898978, 2019). "However, the significance of RRM2 expression in prognosis of breast cancer remains largely unclear." (PMID 30898978, 2019). "In our study, the expression of Rrm2 increased throughout the breast cancer development in PyMT mice (log2 fold change in hyperplasia, adenoma/MIN, early carcinoma, late carcinoma is 2.5, 4.0, 2.7, and 2.8, respectively) and may serve as potential biomarker for diagnosis as well as drug target." (PMID 28212608, 2017). "Similar to the way that HER2 is used to identify subtypes that are likely to respond to trastuzumab, RRM2 may be a predictive marker that can stratify the more fatal types of ER-negative breast cancers to identify breast cancer subtypes that will respond to RRM2 inhibitors." (PMID 25213022, 2014). "In breast cancer cells, it has been shown that SNHG16/miR-30a/RRM2 and TTN-AS1/miR-524-5p/RRM2 regulatory axes are involved in malignant proliferation and evasion of apoptosis in tumor cells, respectively." (PMID 41333212, 2025). "miR-204 inhibits breast cancer progression by targeting multiple genes involved in tumor progression such as FOXA1, AP1S3, RIOK1, RRM2, and PRMT5." (PMID 39199587, 2024). "ER− MDA-MB-468 breast cancer cells exhibited an approximately 19-fold higher expression of CCND1 and 4-fold greater expression of RRM2 as compared to MCF7 cells." (PMID 38473336, 2024). "For example, RRM2 was thought as an independent predictive factor of poor prognosis of LUAD and breast cancer." (PMID 38820515, 2024). "The inhibition of ribonucleotide reductase by DDX alone or in combination with palbociclib decreases RRM2 and cyclin D1 and pRb levels in MCF7 ER+ breast cancer cells." (PMID 38473336, 2024). "Ribonucleotide reductase regulatory subunit M2 (RRM2) has been reported to be an oncogene in some malignant tumors, such as lung adenocarcinoma, oral squamous cell carcinoma, glioblastoma, and breast cancer." (PMID 37056349, 2023). "The Kaplan–Meier curve revealed that breast cancer patients with high expression levels of NEAT1, miR‐21, and ribonucleotide reductase regulatory subunit M2 (RRM2) had a worse prognosis compared with those with low levels." (PMID 37310654, 2023). "We next analysed the expression of RRM2, CDC6 and TOP2A in two breast cancer patient datasets pre- and post-endocrine treatment (GSE10281, GSE80077)." (PMID 36997866, 2023). "We next determined the expression of RRM2, CDC6, and TOP2A mRNA and protein in XBP1-knockout sub-clones of MCF7 cells and ER-positive (MCF7, T47D, and BT474) breast cancer cells after treatment with STF083010." (PMID 36997866, 2023). "By inhibiting miR-204-5p and enhancing RRM2 expression, DSCAM-AS1 promoted proliferation and suppressed apoptosis of breast cancer cells, indicating the therapeutic potential of DSCAM-AS1/miR-204-5p/RRM2." (PMID 37508580, 2023). "Our results showing the increased expression of RRM2, CDC6 and TOP2A in XBP1-dependent manner provides a mechanism for their overexpression in breast cancers." (PMID 36997866, 2023). "In breast cancers, miR-4500 exerts antitumor effects by inhibiting the MAPK signaling pathway via ribonucleotide reductase subunit M2 (RRM2)." (PMID 36233210, 2022).